LINC01002 (long independently transcribed non-coding RNA 1002)
Gene: Long non-coding RNA gene on chromosome 19 (181,465 to 246,555, reverse strand). Ensembl gene ENSG00000282508.
Diseases named in the same sentence as LINC01002 in open-access papers:
LINC01002 is named in the same sentence as 2 diseases in open-access papers, as found by Europe PMC text mining. Sharing a sentence is not in itself a finding about the gene and the disease. The quoted sentences say what the papers report.
ischemic stroke (1 paper, 2020). A stroke disorder caused by obstruction of blood flow to the brain, due to thrombotic (local blood clot formation) or embolic (due to a blood clot or other material traveling from another site) event. "LINC01002 and ERVH48-1, as ceRNAs, affect the expression of target genes of ischemic stroke by competitively binding to the hsa-let-7f-5p family." (PMID 33490236, 2020).
LINC01002 also shares sentences with these, for which no sentence is quoted: COVID-19 (1 paper).